SP140 (SP140 nuclear body protein)
Description:
Component of the nuclear body, also known as nuclear domain 10, PML oncogenic domain, and KR body. May be involved in the pathogenesis of acute promyelocytic leukemia and viral infection. May play a role in chromatin-mediated regulation of gene expression although it does not bind to histone H3 tails.
Synonyms: LYSp100; LYSP100-B; LYSP100-A
Tractability: Small molecule: a structure with a bound ligand is known. PROTAC: ubiquitination databases record sites on it; its protein half-life has been measured.
Target class: Epigenetic regulator; Bromodomain; Reader
Gene: Protein-coding gene on chromosome 2 (230,203,110 to 230,316,577, forward strand). Ensembl gene ENSG00000079263.
Subcellular location: Nucleus; Nucleus, PML body; Cytoplasm
Subcellular location (Human Protein Atlas): Nucleoli fibrillar center; Mitochondria
Gene Ontology:
Molecular function: protein binding; DNA-binding transcription factor activity, RNA polymerase II-specific; DNA binding
Biological process: defense response; regulation of transcription by RNA polymerase II
Cellular component: nucleus; cytoplasm; PML body
Genetic constraint (gnomAD): Loss-of-function variants: 42 observed, 72.96 expected, observed/expected ratio (o/e) 0.58, 90% interval 0.45 to 0.75. The upper end of that interval is the gene's LOEUF score, 0.75, which puts it in group 3 of 6, group 1 being the genes least tolerant of losing a copy. Missense variants: 504 observed, 661.1 expected, observed/expected ratio (o/e) 0.76, 90% interval 0.71 to 0.82. Synonymous variants: 201 observed, 220.83 expected, observed/expected ratio (o/e) 0.91, 90% interval 0.81 to 1.02.
Homologues: Orthologues: chimpanzee SP140 (98% identical), macaque SP140 (88% identical), pig SP140 (51% identical), dog SP140 (49% identical), rat Sp100 (29% identical), mouse Sp100 (23% identical), Caenorhabditis elegans hmg-4 (6% identical), Caenorhabditis elegans hmg-3 (6% identical). Paralogues in human: SP140L (51% identical), SP100 (38% identical), SP110 (28% identical), UBTF (9% identical), TOX4 (7% identical), SSRP1 (7% identical), TOX3 (7% identical), TOX (6% identical), TOX2 (6% identical), HMGXB4 (6% identical), SMARCE1 (6% identical), HMGB2 (5% identical), and 8 more.
Diseases named in the same sentence as SP140 in open-access papers:
SP140 is named in the same sentence as 54 diseases in open-access papers, as found by Europe PMC text mining. Sharing a sentence is not in itself a finding about the gene and the disease. The quoted sentences say what the papers report.
multiple sclerosis (10 papers, 2021 to 2025). A progressive autoimmune disorder affecting the central nervous system resulting in demyelination. "In humans, loss-of-function mutations in SP140 are associated with immune disorders such as multiple sclerosis and B cell cancers." (PMID 40500448, 2025). "Genome-wide association studies (GWASs) have demonstrated that SNPs in SP140 are associated with Crohn’s disease (CD), multiple sclerosis, and chronic lymphocytic leukemia." (PMID 39162523, 2024). "The expression of immune-related genes associated with multiple sclerosis (MS) and other autoimmune diseases is regulated by SP140." (PMID 34149798, 2021). "Variants of the SP140 (ENSG00000079263) gene are known to be related to multiple sclerosis (MS) and chronic lymphocytic leukemia." (PMID 33931127, 2021). "SP140 is an epigenetic reader containing bromodomain, the loss-of-function mutation of which is correlated with multiple autoimmune diseases, such as Crohn’s disease and multiple sclerosis." (PMID 38225273, 2024). "In addition, the SNPs on Sp140 associate with autoimmune diseases, such as Crohn’s disease and multiple sclerosis, in humans, where MCs have been proposed to potentially contribute to the pathogenesis." (PMID 34156030, 2021). "SNPs on SP140 associate with Crohn’s disease and multiple sclerosis in humans." (PMID 34156030, 2021). "Notably, the exclusion of the same exon in SP140 transcript isoforms has also been associated with risk alleles for other diseases including multiple sclerosis." (PMID 33926512, 2021). "Finally, we speculate that the antiviral activity of SP140 could explain why multiple sclerosis and B cell cancers are linked to SP140 mutations, as infection with MHV68-related viruses Epstein–Barr virus and Kaposi’s sarcoma-associated herpesvirus are associated with these immune disorders." (PMID 40500448, 2025). "In future work, it will be of interest to determine whether individuals with SP140 mutations are more susceptible to infection with Epstein–Barr virus and Kaposi’s sarcoma-associated herpesvirus, which could lead to increased risk of multiple sclerosis and B cell cancers." (PMID 40500448, 2025). "SP140 is involved in various immune-related diseases such as Crohn's disease, chronic lymphocytic leukemia, and multiple sclerosis and has recently been identified as the main regulator of the immune response in ovarian cancer." (PMID 35368888, 2022).
chronic lymphocytic leukemia (8 papers, 2013 to 2024). "Single nucleotide polymorphisms in SP140 gene have been correlated with lower expression of SP140 together with higher incidence of chronic lymphocytic leukemia and multiple myeloma." (PMID 26347895, 2015). "Similar to SP100, the SP140 and SP140L proteins are autoantigens in primary biliary cirrhosis, and SP140 is active in chronic lymphocytic leukemia." (PMID 34298819, 2021). "High expression of SP140 was also observed in chronic lymphocytic leukemia." (PMID 35986286, 2022).
Crohn disease (8 papers, 2021 to 2025). A gastrointestinal disorder characterized by chronic inflammation involving all layers of the intestinal wall, noncaseating granulomas affecting the intestinal wall and regional lymph nodes, and transmural fibrosis. "In humans, the Sp140 hypomorphic alleles were associated with susceptibility to multiple sclerosis and Crohn’s disease." (PMID 41037321, 2025). "Genetic polymorphisms and epigenetic modifications in the SP140 locus have been linked to Crohn’s disease (CD), suggesting a role in inflammation." (PMID 35986286, 2022). "Moreover, the Sp140 mutations predicted the responsiveness of Crohn’s disease patients to anti-TNF therapy, suggesting its role in regulating TNF response." (PMID 41037321, 2025). "Crohn’s disease–associated SNPs on SP140 alter the mRNA splicing and skip its exon 7 in humans." (PMID 34156030, 2021).
autoimmune disease (5 papers, 2021 to 2025). A disorder resulting from loss of function or tissue destruction of an organ or multiple organs, arising from humoral or cellular immune responses of the individual to their own tissue constituents. "SP140 has been implicated in CD and other autoimmune diseases through genetic and epigenetic association studies." (PMID 35986286, 2022).
primary biliary cirrhosis (4 papers, 2015 to 2025). "Additionally, SP140 alterations have been associated with autoimmune diseases like primary biliary cirrhosis (PBC), where the immune system mistakenly attacks the body's own tissues." (PMID 38468469, 2024). "In addition, SP100 and SP140 are autoantigenic targets in primary biliary cirrhosis (PBC), a slowly progressing autoimmune disease that destroys primarily the bile canaliculi and leads to cholestasis." (PMID 26347895, 2015). "Similarly to SP100 and SP140 protein, we detected serum autoantibodies to SP140L in patients with primary biliary cirrhosis using luciferase immunoprecipitation system and immunoblotting assays." (PMID 26347895, 2015).
tuberculosis (4 papers, 2021 to 2024). A chronic, recurrent infection caused by the bacterium Mycobacterium tuberculosis. "In contrast, in Sp140-/- mice with tuberculosis, interstitial pulmonary macrophages produced IFN-I, perhaps after having been primed by IFN-I from plasmacytoid dendritic cells, which were more prolific producers." (PMID 38866980, 2024). "As we previously demonstrated, the susceptibility of Sp140−/− mice to Mtb is driven by type I IFN, and mirrors the correlation between type I IFN and active tuberculosis disease seen in humans." (PMID 38029747, 2023). "Our Sp140−/− mice were generated on a pure C57BL/6J background, enabling the use of existing genetic tools to dissect tuberculosis pathogenesis." (PMID 38029747, 2023).
leukemia (3 papers, 2022 to 2025). A malignant (clonal) hematologic disorder, involving hematopoietic stem cells and characterized by the presence of primitive or atypical myeloid or lymphoid cells in the bone marrow and the blood. "Out of 17 genes that mapped to the DISEASE database, 7 have been linked to pathogenesis of human CLL and/or other leukemias (Birc3, Wnt5a, SP140, Atr, Lyn, CD274, and Flt3), and SIFT analysis revealed that the detected mutation in Lyn is likely deleterious." (PMID 34417556, 2022). "The DNAm levels at three individual CG dinucleotides (CpG sites) in the genes MYO1D, STK17A, and SP140 correlated with CD34+ cell numbers in mobilized peripheral blood and with blast counts in leukemia." (PMID 37370186, 2023).
cervical cancer (2 papers, 2022 to 2025). A primary or metastatic malignant neoplasm involving the cervix. "Expression patterns were highly variable: high SP140 expression was linked to poor prognosis in ccRCC, glioma, LSCC, ovarian and cervical cancers but associated with better prognosis in AML, osteosarcoma, HNSCC, lung cancer, and metastatic melanoma." (PMID 41188771, 2025). "Further studies are necessary to elucidate mechanism of SP140/FBXO6 in cervical cancer." (PMID 35368888, 2022).
colitis (2 papers, 2021 to 2022). Inflammation of the colon. "Hematopoietic stem cell‐specific knockdown of Sp140 in mice resulted in exacerbated dextran sulfate sodium‐induced colitis, and low SP140 levels in human CD intestinal biopsies correlated with relatively lower intestinal inflammatory cytokine levels and improved the response to anti‐TNFα therapy." (PMID 34358410, 2021). "Unfortunately, due to poor in vivo pharmokinetics (data not shown), GSK761 was not suitable to evaluate the effects of SP140 inhibition in in vivo animal models of colitis." (PMID 35986286, 2022).
glioma (2 papers, 2024 to 2025). A benign or malignant brain and spinal cord tumor that arises from glial cells (astrocytes, oligodendrocytes, ependymal cells). "On the other hand, SP140, another member of this family, is elevated in glioma and is associated with disease progression." (PMID 41188771, 2025). "SP140, the most studied member, showed divergent associations: high expression worsened outcomes in ccRCC, glioma, and gynecologic cancers but improved survival in AML, osteosarcoma, and melanoma." (PMID 41188771, 2025). "While SP100 acts as a tumor suppressor in malignancies like breast cancer, SP110 and SP140 are implicated in promoting oral squamous cell carcinoma and glioma progression, respectively, and SP140L is linked to poor prognosis in pancreatic adenocarcinoma." (PMID 41188771, 2025). "This analysis incorporated clinical factors, including WHO grading, IDH mutation status, age, and SP140 expression, to predict 1‐year, 2‐year, and 3‐year survival rates following glioma diagnosis." (PMID 38468469, 2024). "SP140 was further announced as a practical tool for predicting the survival of glioma patients and also as an effective treatment target." (PMID 41188771, 2025). "In solid tumors, this review uncovers novel tissue-specific roles: SP140 promotes glioma progression but protects osteosarcoma, while SP100 suppresses breast and lung cancers yet exacerbates PAAD." (PMID 41188771, 2025). "To further explore the oncogenic roles of SP140 in glioma, we differential expression analysis on mRNA transcripts of all coding proteins between the high and low expression of SP140 groups." (PMID 38468469, 2024). "Interestingly, in the glioma and clear cell renal cell carcinoma (ccRCC) tumor microenvironments, expression of SP140 is dysregulated, resulting in altered macrophage polarization and immune evasion." (PMID 41188771, 2025). "SP140 inhibitor can suppress glioma progression via TRIM22/PI3K/AKT signaling pathway." (PMID 41188771, 2025). "In vivo studies within murine glioma models show that GSK761 inhibits glioma progression via TRIM22 downregulation and downregulation of the PI3K/AKT pathway, which suggests that SP140 inhibition may allow for reduced glioma invasiveness." (PMID 41188771, 2025). "Our research findings indicated that in gliomas, SP140 inhibitors could suppress the PI3K/AKT signaling pathway by downregulating TRIM22, thus inhibiting glioma proliferation and invasion." (PMID 38468469, 2024). "Finally, we delved into the potential mechanisms through which SP140 regulates glioma proliferation and invasion." (PMID 38468469, 2024). "Mechanistically, studies suggest that SP140 promotes PD-L1 expression through STAT1/IRF1 activation in tumor-associated macrophages, which may explain its association with immune escape and poor prognosis in cancers such as glioma and ccRCC." (PMID 41188771, 2025). "Furthermore, we investigated the mechanisms by which SP140 influences glioma, revealing that it may regulate glioma proliferation and invasion through the TRIM22‐mediated modulation of the PI3K/AKT signaling pathway." (PMID 38468469, 2024). "SP140 inhibitor could suppress glioma progress via TRIM22/PI3K/AKT signaling pathway." (PMID 38468469, 2024). "The effect of SP140 inhibitor in glioma progress and TRIM22/PI3K/AKT signaling pathway was confirmed in U251/U87 glioma cells." (PMID 38468469, 2024). "These insights suggest SP140 inhibitors (e.g., GSK761 in glioma) and SP100-AS1 silencing (in CRC) as promising strategies, while SP100’s IFN-α responsiveness in breast cancer could enhance immunotherapy." (PMID 41188771, 2025). "Furthermore, SP140 and TRIM22 coexpressed in glioma cells with high level of vascular proliferation, TRIM22 is closely associated with the immune cell infiltration." (PMID 38468469, 2024). "SP100 and SP140 showed a higher expression in the glioma tissue than in normal tissue." (PMID 38468469, 2024).
glioma (continued). "In terms of mRNA expression levels, SP140 but not other members of SP family could be identified as an independent predictor of glioma prognosis although involving clinical characteristics." (PMID 38468469, 2024).
head and neck squamous cell carcinoma (2 papers, 2022 to 2024). A squamous cell carcinoma that arises from any of the following anatomic sites: lip and oral cavity, nasal cavity, paranasal sinuses, pharynx, larynx, and salivary glands. "SP110 and SP140 showed high rates of nonsynonymous mutations in head and neck squamous cell carcinoma." (PMID 38468469, 2024). "Besides, SP140 is highly expressed in tumor‐associated macrophages across head and neck squamous cell carcinoma, and higher expression of SP140 in the tumors was associated with higher tumor mutation burden, improved survival, and a favorable response to immunotherapy." (PMID 38468469, 2024). "SP140 might be a biomarker in head and neck squamous cell carcinoma." (PMID 36276071, 2022).
multiple myeloma (2 papers, 2015 to 2022). "SP140 was one of the mutations identified in hyperdiploid multiple myeloma samples." (PMID 34417556, 2022).
osteosarcoma (2 papers, 2020 to 2025). A usually aggressive malignant bone-forming mesenchymal neoplasm, predominantly affecting adolescents and young adults. "Two hub genes, SIGLEC7 and SP140, were positively associated with outcomes in osteosarcoma patients." (PMID 32190007, 2020). "In examining the role of SP140 in 225 patients with osteosarcoma, this protein, in addition to having a protective role, by being overexpressed promises a better prognosis." (PMID 41188771, 2025). "By cross-validation with the GEO dataset, an independent cohort of 42 osteosarcoma cases, we identified two prognostic immune-related genes (Siglec7, SP140) consistent with the Target database." (PMID 32190007, 2020).
rheumatoid arthritis (2 papers, 2022 to 2023). A chronic, systemic autoimmune disorder characterized by inflammation in the synovial membranes and articular surfaces. "In addition, our previous study demonstrated upregulated expression of SP140 in a range of inflammatory diseases such as CD, rheumatoid arthritis (RA), and systemic lupus erythematosus, implicating SP140 in immune-mediated pathogenesis." (PMID 37232738, 2023).
Breast Invasive Carcinoma (1 paper, 2021). "Of importance, lower expression levels of the PDE9A, Iqca1, Sirpb1b, CD244, SP140, and PIP5k1b genes was found in the BC patients with unfavorable prognosis in terms of 5-year survival analysis (dataset of Breast Invasive Carcinoma [n = 1075] from TCGA)." (PMID 33426510, 2021).
clear cell renal cell carcinoma (1 paper, 2025). "Similarly, in clear cell renal cell carcinoma, high SP140 expression is linked to poorer overall survival, positioning it as a potential prognostic biomarker." (PMID 41188771, 2025).
cryptococcal infection (1 paper, 2025). "Here, our findings support that IFN1 is unnecessary for effective fungal control and that Sp140 does not play a relevant role in the immune phenotype generated during C3HeB/FeJ latent cryptococcal infection." (PMID 39807873, 2025).
lung carcinoma (1 paper, 2025). "Lung cancer mirrored this, with high SP100 and SP140 expression linked to better prognosis, involving apoptotic (TNF-α, caspase) and TAM-mediated immune pathways, respectively." (PMID 41188771, 2025). "Due to SP140’s ability to enhance STAT1/IRF1 signaling and increase PD-L1 expression in tumor-associated macrophages, it has emerged as a crucial biomarker of immune evasion and predictor of immunotherapy resistance in cancers such as HNSCC and lung cancer." (PMID 41188771, 2025).
malaria (1 paper, 2023). Malaria is a serious and sometimes fatal disease caused by a parasite that commonly infects a certain type of mosquito which feeds on humans. "We previously reported an important role for type I IFNs in the development of human Tr1 cells during malaria, but did not identify SP140 as a DEG in our comparison of human Th1 and Tr1 cells." (PMID 36594463, 2023).
metastatic melanoma (1 paper, 2025). A melanoma that has spread from its primary site to another anatomic site. "By activating STAT1/IRF1 signaling through IFN-γ in tumor-associated macrophages, SP140 promotes PD-L1 expression, which has been reported as both a therapeutic target and a predictive biomarker of immunotherapy response in cancers such as metastatic melanoma and head and neck neoplasms." (PMID 41188771, 2025).
Mycobacterium infection (1 paper, 2025). Infections with bacteria of the genus Mycobacterium. "Sp140 deficiency replicates the C3HeB/FeJ immune phenotype in C57Bl/6J mice during Mycobacterium infection." (PMID 39807873, 2025). "Our findings highlight that the role of Sp140 in the C3HeB/FeJ immune response to latent Cryptococcus infection differs from that seen in Mycobacterium infection." (PMID 39807873, 2025).
myeloid leukemia (1 paper, 2025). A clonal proliferation of myeloid cells and their precursors in the bone marrow, peripheral blood, and spleen. "These epigenetic differences highlight SP140’s dual role, modulated by methylation status, and highlight its potential as a prognostic marker in myeloid leukemias." (PMID 41188771, 2025).
promyelocytic leukemia (1 paper, 2020). "Bright (B-cell regulator of IgH transcription) interacts with Sp100, which is a component of promyelocytic leukemia (PML) nuclear bodies and the lymphoid restricted homolog of Sp100, LYSp100/Sp140." (PMID 33409278, 2020).
psoriasis (1 paper, 2013). An autoimmune condition characterized by red, well-delineated plaques with silvery scales that are usually on the extensor surfaces and scalp. "After technical validation, we used an independent sample of patients and controls recruited from the same University Hospitals to validate the association of SPATS2L, KLF6 and SP140 genes with the activation of T cells in psoriasis." (PMID 24267790, 2013).